PADI6 (peptidyl arginine deiminase 6)
Description:
Structural constituent of cytoplasmic lattices, which plays a key role in early embryonic development. Cytoplasmic lattices consist in fibrous structures found in the cytoplasm of oocytes and preimplantation embryos. They are required to store maternal proteins critical for embryonic development, such as ribosomal proteins and proteins that control epigenetic reprogramming of the preimplantation embryo, and prevent their degradation or activation. In contrast to other members of the family, does not show protein-arginine deiminase activity due to its inability to bind Ca(2+).
Synonyms: hPADVI; OZEMA16; PREMBL2
Tractability: PROTAC: a small molecule that binds it is known.
Target class: Enzyme; Hydrolase
Gene: Protein-coding gene on chromosome 1 (17,372,196 to 17,401,699, forward strand). Ensembl gene ENSG00000276747.
Subcellular location: Cytoplasm; Cytoplasmic vesicle, secretory vesicle, Cortical granule; Nucleus
Pathways (Reactome):
Chromatin organization: Chromatin modifying enzymes
Developmental Biology: M-decay: degradation of maternal mRNAs by maternally stored factors
Gene Ontology:
Molecular function: identical protein binding; protein binding; protein-arginine deiminase activity; structural constituent of cytoplasmic lattice; tubulin binding; calcium ion binding
Biological process: protein storage; embryonic cleavage; epigenetic programming in the zygotic pronuclei; establishment of spindle localization; positive regulation of embryonic development
Cellular component: cytoplasm; cytoplasmic lattice; cell cortex; cortical granule; nucleus; subcortical maternal complex; intermediate filament cytoskeleton; ooplasm
Genetic constraint (gnomAD): Loss-of-function variants: 65 observed, 80.29 expected, observed/expected ratio (o/e) 0.81, 90% interval 0.66 to 1. The upper end of that interval is the gene's LOEUF score, 1, which puts it in group 4 of 6, group 1 being the genes least tolerant of losing a copy. Missense variants: 850 observed, 879.68 expected, observed/expected ratio (o/e) 0.97, 90% interval 0.91 to 1.02. Synonymous variants: 395 observed, 353.09 expected, observed/expected ratio (o/e) 1.12, 90% interval 1.03 to 1.22.
Homologues: Orthologues: chimpanzee PADI6 (99% identical), macaque PADI6 (96% identical), dog PADI6 (77% identical), rabbit PADI6 (76% identical), pig PADI6 (73% identical), rat Padi6 (69% identical), guinea pig PADI6 (67% identical), mouse Padi6 (66% identical), zebrafish padi2 (37% identical). Paralogues in human: PADI4 (44% identical), PADI1 (44% identical), PADI2 (43% identical), PADI3 (43% identical).
Diseases named in the same sentence as PADI6 in open-access papers:
PADI6 is named in the same sentence as 22 diseases in open-access papers, as found by Europe PMC text mining. Sharing a sentence is not in itself a finding about the gene and the disease. The quoted sentences say what the papers report.
Infertility (13 papers, 2010 to 2024). "It was not until 2016 that a similar human PADI6 phenotype was reported after whole-exome sequencing revealed homozygous premature PADI6 nonsense mutations and compound heterozygous mutations in the genomes of infertile women." (PMID 37778376, 2023). "Whole-exome sequencing of 26 infertile women has led to the identification of 32 pathogenic PADI6 mutations that, when homozygous or compound heterozygous, are associated with female infertility." (PMID 37778376, 2023). "For patients diagnosed with infertility caused by PADI6 mutations, genetic counselling is recommended." (PMID 36088419, 2022). "Loss of PADI6 results in infertility, marked by defects in protein synthesis and defective embryonic gene activation at the two-cell stage." (PMID 34805139, 2021). "For PADI6 mutations inducing early infertility, this affects the expression of certain genes essential for cytokinesis during the early stages of embryogenesis, such as that of cofilin-1 (CFL1), which is involved in the organization of the actin cytoskeleton." (PMID 33228136, 2020). "Furthermore, previous research has linked PADI6 to other reproductive deficiencies, strengthening the association between PADI6 and infertility, miscarriages, and molar pregnancies." (PMID 38562607, 2024). "A novel homozygous mutation in PADI6 was identified in the present study, which can account for early embryo arrest caused by genetic abnormalities and expand the spectrum of genetic causes and phenotypes of human infertility." (PMID 36088419, 2022). "PADI6 has been shown to participate in the subcortical maternal complex and through its recessive variants it has been demonstrated that, its misexpression was related with early embryonic arrest and infertility." (PMID 34361119, 2021). "Similarly, women carrying a MEG mutation (e.g., NLRP5, NLRP7, and PADI6) experience a range of reproductive outcomes, including hydatidiform moles, periods of infertility, reproductive loss, offspring with multi-locus imprinting disorders, and unaffected children." (PMID 32516339, 2020). "The importance of PADI6 was revealed in 2007 by Coonrod and co-workers, who demonstrated that PADI6 knock-out female mice were infertile, with embryos arresting at the 2-cell stage." (PMID 37778376, 2023). "In this study, we identified two novel homozygous variants (c.487T > C [p.Cys163Arg], and c.1425G > A [p.Trp475*]) in PADI6 in two infertile patients from a cohort of 75 females with the phenotype of early embryonic arrest, which caused recurrent ART failure." (PMID 35433708, 2022). "MATER co-localizes with PADI6 within the CPL of mouse oocytes, and loss of MATER results in infertility, marked by developmental arrest in two-cell embryos, similar in many ways to the phenotype caused by loss of maternal PADI6." (PMID 34805139, 2021). "Our findings expand the mutational spectrum of PADI6 and TLE6 associated with embryonic developmental arrest and deepen our understanding of the genetic causes of infertility with recurrent ART failure." (PMID 34036456, 2021). "PADI6 has therefore become an important gene in the screening of early infertility post-fertilization." (PMID 33228136, 2020). "While the involvement of PADI6 in infertility is well demonstrated, its role in imprinting disorders is less well established." (PMID 32928291, 2020). "Alternatively, genes with no reported COI are enriched in gene sets associated with germ cell development and implicated in infertility mainly caused by spermatogenic failure (e.g., CATIP, CFAP65, CEP19) and oocyte/zygote/embryo maturation arrest (e.g., PADI6, REC114, WEE2)." (PMID 39202055, 2024). "Additionally, like PADI6, numerous SCMC gene mutations have been reported in either infertile women or women with fertility issues and/or in children with MLID, suggesting the function of PADI6 in maternal imprinting is also linked with the SCMC." (PMID 37778376, 2023).
Infertility (continued). "PADI6 absence in knockout mice led to the dispersal of cytoskeletal sheets in oocytes, and in infertile PADI6 compound-heterozygous women oocytes underwent a reduced amount of RNA polymerase II, essential for ZGA and consequent direct cleavages, which arrest embryo development." (PMID 35317853, 2022). "Thus, PADI6 is related to different tissue-specific processes, namely PADI6 presents with a high expression on the oocyte, regulating its activation thus arising to be an important maternal infertility factor." (PMID 34361119, 2021). "Furthermore, given that MATER and PADI6 are both expressed in human oocytes, a better understanding of the role of murine MATER, PADI6, and the lattices in early developmental events may provide insight into human infertility." (PMID 20830304, 2010).
female infertility (9 papers, 2020 to 2025). Diminished or absent ability of a female to achieve conception. "We and other groups previously found that biallelic mutations in PADI6 caused female infertility manifesting as early embryonic arrest." (PMID 35433708, 2022). "Our study expands the mutational spectrum of PADI6 and further supports the causality between PADI6 mutations and female infertility." (PMID 35433708, 2022). "Our study broadens the mutational spectrum of PADI6 and provides the further relationship between PADI6 variants and female infertility." (PMID 35433708, 2022). "Several studies have indicated PADI6 variants as the cause of female infertility, but its role in imprinting disorders is less well established." (PMID 32928291, 2020). "In humans, homozygous loss-of-function mutations of PADI6 are associated with female infertility and hydatidiform mole." (PMID 32928291, 2020). "However, PADI6 has key roles in oocyte maturation and early embryonic development, with its loss leading to female infertility and early embryo arrest." (PMID 37778381, 2023). "Human PADI6 variants have been associated with female infertility and hydatidiform mole." (PMID 32928291, 2020). "Several studies have demonstrated that mutations in SCMC‐related genes (TLE6, PADI6, NLRP2, NLRP5, and KHDC3L) cause human female infertility in the form of an exhibition of EEA and fragmentation." (PMID 35946397, 2022). "The absence of PADI6 protein results in the dispersal of cytoskeletal sheets in oocytes, which ultimately leads to female infertility." (PMID 35692832, 2022). "PADI6 is a crucial member of SCMC, which has been reported to result in female sterility and is associated with a phenotype of early human embryonic arrest possibly due to impairment of embryonic genome activation (ZGA)." (PMID 34036456, 2021). "In conclusion, the present study identified novel mutations in the SCMC genes PADI6 and TLE6 and expanded the spectrum of genetic causes of female infertility with recurrent ART failure characterized by embryonic arrest in development." (PMID 34036456, 2021). "Our study suggests that hypomorphic PADI6 mutations cause MLID, while complete loss-of-function variants lead to female infertility." (PMID 32928291, 2020). "Therefore, the loss and mutation of PADI6 destabilizes SCMC, resulting in abnormal oocyte maturation, fertilization failure, early embryonic developmental arrest, multilocus imprinting disorder, molar pregnancy, miscarriage, and female infertility." (PMID 37020554, 2023).
hydatidiform mole (5 papers, 2020 to 2023). A gestational trophoblastic disorder characterized by marked enlargement of the chorionic villi, hyperplasia of the villous trophoblastic cells and hydropic changes. "Patients with PADI6 mutation showed early embryonic arrest, zygotic cleavage failure, recurrent hydatidiform moles and other different phenotypes." (PMID 37712067, 2023). "Although most mutated PADI6 proteins cause early embryonic developmental disorders, two variants (c.1793A>G, p.(Asn598Ser) and c.2045G > A, p.(Arg682Gln) caused recurrent hydatidiform moles." (PMID 37712067, 2023). "In addition to the early embryonic arrest phenotype, PADI6 mutations in human also result in recurrent hydatidiform moles." (PMID 37712067, 2023). "Other studies confirm that PADI6 does not only cause (early) pregnancy losses and recurrent hydatidiform moles, but maternal effect variants in this gene cause chromosomal aberrations and disturbed imprinting, producing children with Beckwith–Wiedemann syndrome or Silver–Russell syndrome." (PMID 36088419, 2022). "In addition, in hydatidiform moles, PADI6 can regulate trophoblast cell migration-invasion through Hippo/YAP1 Pathway." (PMID 37712067, 2023).
Beckwith-Wiedemann syndrome (1 paper, 2020). Beckwith-Wiedemann syndrome (BWS) is a genetic disorder characterized by overgrowth, tumor predisposition and congenital malformations. "We have identified by whole-exome sequencing analysis four cases of Beckwith-Wiedemann syndrome with multi-locus imprinting disturbance whose mothers are carriers of PADI6 variants." (PMID 32928291, 2020).
lung carcinoma (1 paper, 2023). "In each meta-analysis of breast and lung cancer across BBJ1 and UKB, we identified one locus newly satisfying the genome-wide significance threshold (breast: rs2800691 at PADI6 on 1p36, P = 3.6 × 10−8; lung: rs2076295 at DSP on 6p24, P = 2.6 × 10−8)." (PMID 37340002, 2023).
melanoma (1 paper, 2013). A malignant, usually aggressive tumor composed of atypical, neoplastic melanocytes. "Interestingly, rs7538876 and several other correlated variants map within the PADI6, which is involved in cytoskeletal organization, but due to its expression in early embryogenesis, its role in melanoma progression is yet to be elucidated." (PMID 24188633, 2013).
rheumatoid arthritis (1 paper, 2012). A chronic, systemic autoimmune disorder characterized by inflammation in the synovial membranes and articular surfaces. "A total of 320 SNPs from the PADI locus (including PADI1, PADI2, PADI3, PADI4 and PADI6 genes) were genotyped in 1,238 RA cases and 1,571 control subjects from the Malaysian Epidemiological Investigation of Rheumatoid Arthritis (MyEIRA) case-control study." (PMID 23164236, 2012).
Silver-Russell syndrome (1 paper, 2020). Silver-Russell syndrome is characterized by growth retardation with antenatal onset, characteristic facies and limb asymmetry. "It is also worth to mention that three of the four MLID cases with PADI6 variants described so far displayed a Silver-Russell syndrome (SRS) phenotype." (PMID 32928291, 2020). "In addition, biallelic or monoallelic missense PADI6 variants have been linked with three cases of Silver-Russell syndrome and one case of BWS." (PMID 32928291, 2020).
cancer (5 papers, 2019 to 2023). A tumor composed of atypical neoplastic, often pleomorphic cells that invade other tissues. "The single cancer GWAS/meta-analysis found five risk variants of the specific individual cancers across East Asians and Europeans (e.g., PADI6 on 1p36 and DSP on 6p24)." (PMID 37340002, 2023). "The role of the PADI family (except PADI6) in cancer is still under debate." (PMID 37020554, 2023).
adenocarcinoma (1 paper, 2020). A common cancer characterized by the presence of malignant glandular cells. "In vitro lung epithelial and adenocarcinoma alveolar cell models revealed that PADI1, PADI2 and PADI4 mRNA levels were elevated, but PADI3 and PADI6 mRNA levels were reduced in SARS-CoV-2-infected NHBE cells." (PMID 32629995, 2020).
PADI6 also shares sentences with these, for which no sentence is quoted: basal cell carcinoma (1 paper); breast carcinoma (1); COVID-19 (1); developmental delay (1); epilepsy (1); Lewy body disease (1); lymphoma (1); mammary adenocarcinoma (1); mesothelioma (1); mixed germ cell-sex cord stromal tumour (1); Parkinson disease (1); tumour (1).